TFRC (transferrin receptor)
Diseases named in the same sentence as TFRC in open-access papers (continued):
Sharing a sentence is not in itself a finding about the gene and the disease.
Insulin resistance (17 papers, 2013 to 2025). Increased resistance towards insulin, that is, diminished effectiveness of insulin in reducing blood glucose levels. "CircRNA-TFRC (transferrin receptor, TFRC) is associated with insulin resistance, and the overexpression of TFRC can aggravate the risk of type 2 diabetes and metabolic diseases." (PMID 31341180, 2019). "CircRNA-TFRC (transferring receptor, TFRC) is a circRNA that is associated with insulin resistance." (PMID 32815547, 2020). "In their study on human skeletal muscle cells, they found that palmitic acid induced cellular iron overload by upregulating both the transferrin receptor protein and mRNA levels, leading to insulin resistance and glucose intolerance." (PMID 37513632, 2023). "Preclinical studies have connected the transferrin receptor and SFAs in the development of insulin resistance." (PMID 37513632, 2023). "Furthermore,individuals are more likely to suffer from CVD due to increased blood glucoselevels, insulin resistance, inflammation, and reactive oxygen species.Several lines of evidence suggest that inflammatory cytokines and reactive oxygenspecies can regulate tissue transferrin receptor expression." (PMID 39742215, 2024). "In elderly subjects, negative correlations between serum ferritin and soluble transferrin receptor (sTfR) and osteocalcin led to the conclusion that factors related to iron metabolism may contribute to the development of insulin resistance and type 2 diabetes." (PMID 39872315, 2024).
heart failure (16 papers, 2018 to 2025). Inability of the heart to pump blood at an adequate rate to meet tissue metabolic requirements. "TFRC in cardiomyocytes promoted heart failure (HF) development through inducing macrophage infiltration and activation via the STAT3‐Ccl2 signaling, and TFRC expression in cardiomyocytes was regulated by HIF‐1α during HF." (PMID 37647427, 2023). "Besides, it was observed that SGLT2 inhibitors in patients with heart failure decreased hepcidin and ferritin levels and increased transferrin receptor protein." (PMID 40151322, 2025). "TFRC can transfer Fe2+ into cytoplasm, and increased cytosolic Fe2+ further facilitates the synthesis of ATP in cardiomyocytes and heme in erythroid precursors, which has been believed as a possible mechanism for the beneficial effect on major heart failure events of SGLT2i." (PMID 38044448, 2023). "A systematic review of observational studies in English from 2010 to 2022 was conducted using PubMed, with keywords of “Heart Failure” and respective iron metabolism biomarkers (“Ferritin”, “Hepcidin”, “TSAT”, “Serum Iron”, and “Soluble Transferrin Receptor”)." (PMID 36982717, 2023). "In a mouse model lacking cardiomyocyte transferrin receptor 1 (TfR1), iron levels in the heart were severely reduced, resulting in fatal heart failure in the second week of age, in part, due to failure of mitochondrial respiration." (PMID 31466321, 2019).
hemochromatosis (16 papers, 2010 to 2025). A disorder of iron metabolism characterized by a triad of HEMOSIDEROSIS; LIVER CIRRHOSIS; and DIABETES MELLITUS. "Iron transport via transferrin seems not to contribute significantly to continuous hepatic iron loading in hemochromatosis, because both transferrin and hepatic transferrin receptor 1 (TfR1) are downregulated under iron-overload conditions." (PMID 32041196, 2020). "Recent data confirm the involvement of genes that encode proteins HFE (hemochromatosis), HJV (haemojuvelin), TfR2 (transferrin receptor), SLC40A1 (ferroportin) in maintaining iron homeostasis by stimulating the production of hepcidin." (PMID 24146699, 2013). "The hemochromatosis gene encodes HFE, a transmembrane glycoprotein which normally associates with transferrin receptor 1 (TfR1) and decreases intracellular iron and ferritin concentrations." (PMID 20670400, 2010). "Hereditary hemochromatosis is caused by mutations in iron regulatory genes, including HAMP (hepcidin gene), HFE (hemochromatosis gene), TFRC (transferrin receptor), HJV (hemojuvelin), and SLC40A1 (ferroportin), and heterozygous mutations in BMP6 pro-peptide." (PMID 40871742, 2025).
bladder cancer (15 papers, 2019 to 2025). "This study discovered an association between TFRC and the immune microenvironment in patients with bladder cancer." (PMID 38336764, 2024). "Besides, many models containing TFRC had been confirmed to have associated with prognosis of bladder cancer." (PMID 38336764, 2024). "The transferrin receptor TFRC is highly expressed in bladder cancer with diagnostic and prognostic value, and the repressed expression of TFRC could inhibit ferroptosis induced by Erastin in bladder cancer cells." (PMID 39329964, 2024). "TFRC plays an important role in bladder cancer, which affects proliferation, invasion, and migration of BLCA." (PMID 38336764, 2024). "We used siRNA to reduce TFRC expression in bladder cancer cells and found that TFRC knockdown inhibited tumor cell proliferation and reduced their invasive ability." (PMID 38336764, 2024). "High expression of circ-TFRC was also detected in bladder cancer patients, and the study showed that circ-TFRC combined with miR-107 exerted a spongy effect and promoted the development of bladder cancer." (PMID 35813288, 2022). "Secondly, we only paid attention to the effect of TFRC on biological functions in bladder cancer, and the specific mechanisms should be further explored in vivo and vitro." (PMID 34362387, 2021). "A previous study indicated that circRNA c-transferrin receptor (cTFRC) regulated TFRC by sponging miR-107 to facilitate bladder carcinoma development." (PMID 32831647, 2020). "In the present study, we explored cTFRC on the EMT process of bladder cancer cell by regulating TFRC expression." (PMID 30782157, 2019). "We first examined the TFRC mRNA levels in a variety of bladder cancer cell lines, and we found that TFRC mRNA expression was correlated with cTFRC expression in BC cell lines." (PMID 30782157, 2019). "Recent studies have shown high expression of transferrin receptor-1 (TfR1) in a variety of tumors including lung, breast, and bladder cancer as well as malignant glioma, but the clinical significance of TfR1 in tumor remains to be confirmed." (PMID 31484533, 2019). "In this study, we found that TFRC is overexpressed in bladder cancer and correlated with poor prognosis of BC patient." (PMID 30782157, 2019). "Furthermore, we confirmed the role of TFRC in bladder cancer cell lines T24 and UMUC-3 through cell experiments." (PMID 38336764, 2024). "In this study, we also found the role of TFRC in the proliferation of bladder cancer." (PMID 38336764, 2024). "TFRC has been reported to be significantly upregulated in a variety of tumors, including bladder cancer and hepatocarcinoma, where it plays a crucial role in promoting tumor cell proliferation, invasion, metastasis, as well as conferring resistance to radiotherapy and chemotherapy." (PMID 39131609, 2024). "In addition, high expression of another circRNA, circ-TFRC, was detected in bladder cancer patients, which means that circ-TFRC promotes bladder cancer progression by binding to miR-107." (PMID 36138829, 2022). "We show that cTFRC is up-regulated in human bladder cancer, and it can efficiently sponge miR-107 to induce TFRC expression, as well as demonstrate that under-expression of cTFRC can effectively inhibit proliferative and invasive ability of bladder cancer cells through targeting miR-107/TFRC axis." (PMID 30782157, 2019). "Mechanistically, cTFRC could function as a ceRNA through harboring miR-107 to abolish the suppressive effect on the target gene TFRC in bladder cancer progression." (PMID 30782157, 2019). "Also, we found that cTFRC was overexpressed in bladder cancer and cTFRC up-regulated TFRC expression in bladder cancer as a “miRNA sponge”." (PMID 30782157, 2019). "TFRC may be a very important target in the treatment of bladder cancer." (PMID 38336764, 2024). "Thus, this may explain the high expression of TFRC in BC patients, but little is known about cTFRC highly expressed in bladder cancer." (PMID 30782157, 2019).
bladder cancer (continued). "However, TFRC has not been reported on bladder cancer progression." (PMID 30782157, 2019).
Cerebral ischemia (14 papers, 2018 to 2025). Restriction of arterial blood supply to the brain associated with insufficient oxygenation to support the metabolic requirements of the tissue. "During cerebral ischemia, large amounts of iron are released from transferrin, inducing iron, transferrin and transferrin receptor (TFR) accumulates intracellularly." (PMID 36210857, 2022). "Administration of drug therapy can alleviate cerebral ischemia injury, and its mechanism includes inhibition of ferroptosis through the transferrin receptor 1/divalent metal transporter 1(TFR1/DMT1) and solute carrier family 7 member 11/glutathione peroxidase 4(SCL7A11/GPX4) pathways." (PMID 36552584, 2022). "Similarly, the upregulation of hypoxia-inducible factor 1-alpha (HIF-1α) after cerebral ischemia results in iron overload, increasing transferrin receptor 1 (TFR1) expression." (PMID 32848555, 2020).
lupus (14 papers, 2014 to 2025). "According to GSEA in KEGG pathways, the TFRC-related pathway mainly focused on “Viral carcinogenesis”, “Alcoholism”, “Neutrophil extracellular trap formation”, “Cell cycle”, and “Systemic lupus erythematosus”." (PMID 40303995, 2025). "recently demonstrated that disease severity in systemic lupus erythematosus (SLE) correlated with transferrin receptor (CD71) expression on TH17 cells." (PMID 40852720, 2025). "Transferrin receptor blockade resulted in lower intracellular iron levels and mTORC1 signalling, which in turn suppressed TH1 and TH17 cells but promoted Treg development and was linked to a less severe course of the disease in lupus‐prone mice." (PMID 40976999, 2025). "Blockage of transferrin receptor led to reduction of intracellular iron and mTORC1 signalling, which in turn inhibited TH1 and TH17 cells but enhanced Treg differentiation and was associated with amelioration of disease severity in lupus-prone mice." (PMID 37554724, 2023). "Through enhanced endosomal recycling, activated T cells raised the transferrin receptor (CD71) and iron absorption, two characteristics that were amplified in lupus T cells." (PMID 40976999, 2025). "Activated T cells upregulated both transferrin receptor (CD71) and iron uptake via increased endosomal recycling, features which were exaggerated in lupus T cells." (PMID 37554724, 2023). "CD25 and CD71 (the transferrin receptor), or costimulatory molecules, such as CD154/CD40L (a type II transmembrane protein belonging to the tumor necrosis factor family) are predominantly expressed at the surface of mature, activated lupus CD4+ T cells that proliferate." (PMID 34744730, 2021).
non-small cell lung carcinoma (13 papers, 1997 to 2023). A group of at least three distinct histological types of lung cancer, including non-small cell squamous cell carcinoma, adenocarcinoma, and large cell carcinoma. "TFRC and KPNB1 have been previously implicated in BC, while PUF60 has been associated with colon and non-small cell lung cancer." (PMID 35453681, 2022). "However, ST6GalNAc3 seems to promote the proliferation of A549 non-small cell lung cancer cells through enhanced expression of transferrin receptor protein 1 (TFR1), which is important for cell proliferation and survival." (PMID 34975914, 2021).
Parkinson disease (13 papers, 2015 to 2026). A progressive degenerative disorder of the central nervous system characterized by loss of dopamine producing neurons in the substantia nigra and the presence of Lewy bodies in the substantia nigra and locus coeruleus. "The present study demonstrates that OX26MAb-/LB509MAb-PEGylated liposomes have affinity for both the ligands transferrin receptor and α-synuclein (neuronal protein that is linked to Parkinson's disease) and that they are internalized by immortalized human cerebral microvascular endothelial cells." (PMID 28031922, 2015). "Additionally, temporal cortical tissues obtained from 27 Parkinson’s disease (PD) patients were analyzed to determine if the anticipated abnormalities in CAMKK2/TF/TFRC were specific to AD or also present in other forms of dementia, specifically PD." (PMID 39669708, 2024). "Postmortem temporal cortex tissues from 74 AD patients, 27 Parkinson’s disease (PD) patients, and 17 CN individuals were analyzed for CAMKK2, TF, and TFRC protein levels by Western blotting." (PMID 39669708, 2024). "PEGylated immunoliposomes were prepared with anti-transferrin receptor OX26 and anti-α-synuclein LB509 antibodies to overcome the BBB in Parkinson's disease." (PMID 28031922, 2015).
type 2 diabetes (13 papers, 2012 to 2025). "Third, the frequency of the G allele at the position 210 of the transferrin receptor gene was significantly higher in type 2 diabetes patients." (PMID 38476599, 2024). "A meta-analysis indicated that elevated serum ferritin was a risk factors for type 2 diabetes, and soluble transferrin receptor-to-ferritin ratio was inversely related to the risk of type 2 diabetes." (PMID 36330096, 2022). "In summary, we identified a novel metabolite locus (MOGAT2) in single variant analyses and four genes (GFRAL, BIN1, TFRC, OR51Q1) within gene-based tests and could show that two previously known mGWAS loci (FADS1 and REV3L) might be relevant for the risk of type 2 diabetes." (PMID 28729637, 2017).
brain cancer (11 papers, 2019 to 2025). A primary or metastatic malignant neoplasm affecting the brain. "Transferrin (TF), for example, targets a transferrin receptor (TFR) that is overexpressed on the surface of brain capillary endothelial cells and malignant brain tumours." (PMID 38130720, 2023). "Transferrin receptors are highly expressed in brain cancers and conjugation of ASOs with anti-transferrin receptor monoclonal antibodies showed a threefold increase in cellular uptake compared to naked ASOs and twofold higher than ASOs conjugated with an aspecific IgG antibody." (PMID 36365206, 2022).
cholangiocarcinoma (11 papers, 2019 to 2025). A carcinoma that arises from the intrahepatic biliary tree (intrahepatic cholangiocarcinoma) or from the junction, or adjacent to the junction, of the right and left hepatic ducts (hilar cholangiocarcinoma). "In addition, transferrin receptor-1 expression augmented in cancer cells of cholangiocarcinoma tissues when compared to normal surrounding tissues and was significantly associated with cholangiocarcinoma metastasis." (PMID 38247453, 2023). "Previous studies found that iron metabolism and iron regulatory proteins were altered in cancer and transferrin receptor-1 was increased in cholangiocarcinoma 32,33." (PMID 32368289, 2020). "They showed that cholangiocarcinoma stem-like cells express high levels of ferritin and low levels of transferrin receptor 1 and ferroportin." (PMID 30717462, 2019). "Finally, using molecular dynamics simulations we recently showed that high mannose N-glycans may affect the dimerization of transferrin receptor protein 1 (coded by the tfrc gene) in cholangiocarcinoma." (PMID 33003435, 2020).
Hunter syndrome (11 papers, 2018 to 2025). "Pabinafusp alfa (JR-141), developed by JCR Pharmaceuticals, consists of human iduronate-2-sulfatase (IDS), the enzyme in which patients with MPS-II are deficient (Hunter syndrome), fused to the C-terminus of the heavy chain of an anti-human transferrin receptor (hTfR) antibody." (PMID 34681597, 2021). "Idursulfase beta, an anti-transferrin receptor antibody fused to iduronate-2-sulfatase based on J-Brain Cargo®, was clinically approved in Japan on 23 March 2021 for the treatment of Hunter syndrome." (PMID 37489365, 2023). "Pabinafusp alfa, which is an anti-mucopolysaccharidosis II drug, consists of iduronate-2-sulfatase (IDS) genetically fused with an anti-transferrin receptor (TfR) antibody." (PMID 40838062, 2023).
lung adenocarcinoma (11 papers, 2016 to 2024). A carcinoma that arises from the lung and is characterized by the presence of malignant glandular epithelial cells. "Indeed, TFRC is a prognostic biomarker associated with tumor burden and survival in lung adenocarcinoma patients." (PMID 37923740, 2023). "In addition, transferrin receptor 1 (TFR1) is negatively regulated by miR-210 and miR-320 causing decreased transferrin uptake and inhibition of proliferation of lung adenocarcinoma A549 cells." (PMID 26560875, 2016). "The TFRC gene has also been deemed useful in genetic panels that provide either early detection or prognosis for lung adenocarcinoma, another NSCLC like SCC." (PMID 39337350, 2024). "TFRC (transferrin receptor) shows CLIFI distributions trending in opposite directions for lung squamous cell carcinoma (higher) and lung adenocarcinoma (lower) indicating potentially discriminatory potential between different cancers of the same organ." (PMID 39624167, 2024). "We found that TFRC mRNA expression was elevated in 20 types of tumor, including breast invasive carcinoma (BRCA), colon adenocarcinoma (COAD), LIHC, and lung adenocarcinoma (LUAD) as compared to normal tissues, providing that upregulated TFRC is a common feature in cancers." (PMID 34389031, 2021).
thyroid cancer (11 papers, 2011 to 2025). "Furthermore, they found that enzyme longevity assurance homologue 2 (LASS2) in association with the transferrin receptor (TFRC) could suppress metastasis in thyroid cancer by regulating ferroptosis, a critical pathway involved in tumor growth and proliferation." (PMID 40149351, 2025). "Research indicated that the expression of TFRC was increased in thyroid cancer tissues compared with normal tissues." (PMID 40529834, 2025). "In thyroid cancer, a low protein level of TFRC was correlated with tumour size (P = 0.017) and lymph node metastasis (P = 0.000)." (PMID 38419028, 2024). "Could the differences in TFRC expression across various studies be related to tumor stage or subtypes of thyroid cancer?" (PMID 40529834, 2025). "Consequently, additional research is required to investigate the function of TFRC in thyroid cancer." (PMID 40529834, 2025). "Meanwhile, AKR1C1, HMGCR, TFRC, SQLE, and PGD were risk factors for thyroid cancer prognosis." (PMID 33928101, 2021). "Therefore, the level of TFRC expression in thyroid cancer remains controversial." (PMID 40529834, 2025). "Currently, no studies have reported the effect of regulating the TFRC expression on thyroid cancer development." (PMID 40529834, 2025). "Our data suggested that AKR1C1 (p < 0.0001), DPP4 (p < 0.0001), GPX4 (p = 0.0001), GSS (p < 0.0001), HMGCR (p < 0.0001), TFRC (p < 0.0001), SQLE (p = 0.0004), and PGD (p = 0.0005) were all significantly highly expressed in thyroid cancer tissues compared to normal tissues." (PMID 33928101, 2021). "The validation of the deregulated protein expression in an independent thyroid carcinoma cohort demonstrates that miRNA-dependent oncogenes comprised in this signature, the transferrin receptor TFRC (CD71) and the E3-ubiquitin ligase DTL, are sharply upregulated in ATC." (PMID 34885022, 2021).
triple-negative breast carcinoma (11 papers, 2012 to 2025). An invasive breast carcinoma which is negative for expression of estrogen receptor (ER), progesterone receptor (PR), and human epidermal growth factor receptor 2 (HER2). "H-chain ferritin (HFtn) is specifically recognized by the transferrin receptor-1 (TfR1), which is overexpressed in various human cancer types, including triple-negative breast cancer." (PMID 37048731, 2023).